SOX4 (SRY-box transcription factor 4)
Diseases named in the same sentence as SOX4 in open-access papers (continued):
Sharing a sentence is not in itself a finding about the gene and the disease.
osteosarcoma (15 papers, 2012 to 2025). A usually aggressive malignant bone-forming mesenchymal neoplasm, predominantly affecting adolescents and young adults. "Compared to the control group, SOX4 mRNA and protein expression were significantly increased in osteosarcoma cells transfected with the miR-497-5p inhibitor." (PMID 37278038, 2023). "In this study, SNHG25 was found to function as an oncogene by promoting osteosarcoma cell proliferation, invasion, and migration via the miR-497-5p/SOX4 axis." (PMID 37278038, 2023). "The 10-year overall survival rate of osteosarcoma patients in the low-expression SOX4 group was 79.5%, and that in the high-expression group was 54.5%, as assessed by the Log-rank test (P=0.04)." (PMID 37278038, 2023). "To date, limited research has been focused on the mechanisms of miR-3195 and SOX4 with respect to osteosarcoma." (PMID 37904207, 2023). "The Log-rank analysis confirmed increased SOX4 expression to be an adverse prognostic factor for osteosarcoma patients (HR=2.195, 95% CI: 1.060–4.545, P = 0.04)." (PMID 37278038, 2023). "The effects of miR-497-5p mimic and inhibitor on SOX4 mRNA and protein expression in osteosarcoma cells were evaluated." (PMID 37278038, 2023). "SNHG25 was determined to function as an oncogene by promoting osteosarcoma cell proliferation, invasion, and migration through the miR-497-5p/SOX4 axis." (PMID 37278038, 2023). "The knockdown of SOX4 expression in osteosarcoma cell lines decreased cell proliferation, migration, and invasion, and it induced apoptosis." (PMID 37278038, 2023). "Specifically, miR-363-3p is capable of suppressing the proliferation and invasion of osteosarcoma cells by targeting SOX4." (PMID 35166647, 2022). "For example, miR-363-3p was proved to repress cell proliferation and invasion in osteosarcoma through targeting SOX4." (PMID 33432525, 2021). "For example, LINC00612 is a ceRNA for miR-214-5p, and it can indirectly up-regulate SOX4 to promote the proliferation, migration, invasion and epithelial-mesenchymal transition of osteosarcoma cells." (PMID 34224294, 2021). "Other stem cell markers such as STAT3 and Sox4 were also strongly expressed in MSCs, while angiopoietin-1 was highly expressed in osteosarcoma cells." (PMID 22852096, 2012). "SOX4 mRNA expression was significantly upregulated in osteosarcoma cells and tissues." (PMID 37278038, 2023). "The results demonstrated SOX4 to be a direct downstream target of miR-497-5p in osteosarcoma cells." (PMID 37278038, 2023). "In addition, the recent upregulation of SOX4 in patients with osteosarcoma and its value as a novel prognostic biomarker have been confirmed." (PMID 37278038, 2023). "In this study, the expression of SOX4 was upregulated in osteosarcoma cell lines and tissues." (PMID 37278038, 2023). "Moreover, SOX4 overexpression rescued the effects of SNHG25 knockdown on osteosarcoma cell proliferation, migration, and invasion." (PMID 37278038, 2023). "Furthermore, a recent investigation exhibited that miR‐363‐3p suppressed tumor progression by directly targeting SOX4 in osteosarcoma." (PMID 35303365, 2022). "Next, we sought to determine whether SNHG25 promotes osteosarcoma progression through SOX4." (PMID 37278038, 2023). "Previous studies have suggested that transcription factors OCT‐1, AP1, SP1, TNF, SOX2, SOX4, and MYC play an important role in the proliferation of osteosarcoma cells." (PMID 34185412, 2021). "HIF2Put promotes the growth of osteosarcoma cells by upregulating the expression of stem cell-related genes OCT4, SOX4 and CD44." (PMID 34048366, 2021). "Moreover, the proliferation, migration, and invasion of osteosarcoma cell lines were considerably inhibited by SNHG25 silencing, and this inhibition was partially reversed following SOX4 overexpression." (PMID 37278038, 2023).
esophageal cancer (14 papers, 2013 to 2025). A primary or metastatic malignant neoplasm involving the esophagus. "We next investigated if loss of SOX4 functionally mimics overexpression of miR-31 in esophageal cancer cells." (PMID 25644061, 2015). "Otherwise, miR-133a suppresses the migration and invasion of esophageal cancer cells by targeting the SOX4." (PMID 30429229, 2018). "We show that miR-31 is repressed in invasive esophageal cancers cell lines and that miR-31 levels inversely correlate with SOX4, EZH2 and HDAC3 expression." (PMID 25644061, 2015). "In esophageal carcinomas, SOX4 promotes tumor progression and invasion." (PMID 35328735, 2022). "LncRNA-UCA1 exerts its oncogenic function in esophageal cancer through acting as the ceRNA of SOX4." (PMID 32795273, 2020). "Besides, SOX4 had been confirmed as a target of miR-133a in esophageal cancer cells by targeting the EMT to suppress the migration and invasion." (PMID 30429229, 2018). "miR-129-3p directly targeted sex-determining region Y-related high-mobility group-box 4 (SOX4), leading to its downregulation and inhibiting cell proliferation, migration, invasion, and EMT in colorectal and esophageal cancer cells." (PMID 39851970, 2025). "In this study, we explore the role of SOX4 and EZH2 in miR-31 repression and the contribution of miR-31 to survival, migration and invasion of aggressive esophageal cancers cells." (PMID 25644061, 2015). "To determine the expression of the complex-forming partners, SOX4, EZH2 and HDAC3, in esophageal cancer cell lines and tissues, we used qRT-PCR." (PMID 25644061, 2015). "Thus, we identified a novel molecular mechanism by which the SOX4, EZH2 and miR-31 circuit promotes tumor progression and potential therapeutic targets for invasive esophageal carcinomas." (PMID 25644061, 2015).
acute myeloid leukemia (11 papers, 2009 to 2025). Acute myeloid leukemia (AML) is a group of neoplasms arising from precursor cells committed to the myeloid cell-line differentiation. "Transcription factor SOX4 reduces mRNA levels of transcription factor PU.1 (SPI 1) in human acute myeloid leukemias." (PMID 25329802, 2014). "SOX4-induced ARHGAP9 overexpression also promoted the progression of acute myeloid leukemia." (PMID 35573654, 2022). "Previous studies demonstrated that Sox4, RasGRP1, RasGRP3, IGF1R, CDK6, and LEF1 are the key oncogenes/tumor suppressor genes in acute myeloid leukemia." (PMID 31242922, 2019). "However, no reports are available regarding the clinical significance of SOX4 in acute myeloid leukemia (AML) and the role of SOX4 in leukemogenesis." (PMID 28841206, 2017). "Chromosomal translocations in some acute myeloid leukemia (AML) cases produce a fusion gene known as ZMYND11-MBTD1 (ZM), which recruits TIP60/KAT5 to stemness-related gene regions, including MYC, HoxA, Meis1, and Sox4." (PMID 41227365, 2025).
lung adenocarcinoma (11 papers, 2008 to 2025). A carcinoma that arises from the lung and is characterized by the presence of malignant glandular epithelial cells. "SOX4 has also been reported to regulate DNA damage repair and promote cisplatin and radiation resistance in lung adenocarcinoma and medulloblastoma." (PMID 39851970, 2025). "In lung adenocarcinoma (LUAD), it modulates the PI3K/AKT pathway via the circGRAMD1B/miR-4428/SOX4/MEX3A axis, enhancing migration, invasion, and EMT." (PMID 40282289, 2025). "For DFS, high SOX4 expression was significantly correlated with poor DFS in cervical squamous cell carcinoma, esophageal adenocarcinoma, LIHC, lung adenocarcinoma, pancreatic ductal adenocarcinoma, and THCA." (PMID 37958409, 2023). "To validate this axis in clinical samples, we downloaded and analyzed the gene expression profiles of HIF1A, CASC15, SOX4, and CTNNB1 (β-catenin) in two lung adenocarcinoma cohorts from TCGA database." (PMID 33407675, 2021). "Trajectory analysis identified ERBB4, SEMA4A, GCNT2 and SOX4 as key factors in AT2 cells that may promote cell proliferation, migration, or epithelial-mesenchymal transition (EMT) during the progression of lung adenocarcinoma (LUAD)." (PMID 41415280, 2025). "SOX-4 was also shown to be highly and differentially expressed in a substantial fraction of small-cell lung carcinoma (SCLC) samples and in a pool of primary lung adenocarcinoma samples, with very low levels of expression in a number of normal essential tissues." (PMID 18498649, 2008).
triple-negative breast carcinoma (10 papers, 2013 to 2025). An invasive breast carcinoma which is negative for expression of estrogen receptor (ER), progesterone receptor (PR), and human epidermal growth factor receptor 2 (HER2). "A recent study demonstrated that the integrin αvβ6–TGF-β–SOX4 pathway regulates multiple signaling events relevant for T cell–mediated tumor immunity in triple-negative breast cancer cells." (PMID 35151689, 2022). "Importantly, it has been reported that forced SOX4 expression promoted immune evasion and resistance to anti-PD-1 immunotherapy in triple-negative breast cancer." (PMID 35800365, 2022). "Our finding may provide a new therapeutic strategy for triple negative breast cancer based on the expression of SOX4." (PMID 33005101, 2020). "We demonstrate that iEVs-335 efficiently and durably restored the endogenous miR-335 pool in human triple negative breast cancer cells, downregulated the expression of the miR-335 target gene SOX4 transcription factor, and markedly inhibited tumor growth in vivo." (PMID 30514916, 2018). "It has been reported that long non-coding RNA ARNILA functioned as a competing endogenous RNA (ceRNA) sponge preventing miR-204 from binding the 3’UTR of SOX4 mRNA, thereby promoting EMT, invasion and metastasis of triple-negative breast cancer." (PMID 30691465, 2019).
acute lymphoblastic leukemia (9 papers, 2015 to 2022). Leukemia with an acute onset, characterized by the presence of lymphoblasts in the bone marrow and the peripheral blood. "Loss or gain-of-function studies in acute lymphoblastic leukemia (ALL) cells identified SOX4 as a critical activator of cell proliferation and survival, and showed that it binds to, and transcriptionally activates, promoters of multiple components of the PI3K/AKT and MAPK signaling pathways." (PMID 34945712, 2021). "In addition, pro-survival SOX4-dependent upregulation of JNK1 (MAPK8) was demonstrated as a critical factor in acute lymphoblastic leukemia." (PMID 29423023, 2018). "SOX4 also promotes progression in BCR-ABL positive acute lymphoblastic leukemia." (PMID 29190894, 2017). "This study aimed to explore the function of circular RNA circPRKCI/miR-20a-5p/SOX4 axis in acute lymphoblastic leukemia (ALL)." (PMID 34695805, 2021). "For example, in acute lymphoblastic leukemia (ALL), mouse genetic studies have also demonstrated that SOX4 binds to and transcriptionally activated promoters of multiple components within the PI3K/AKT and MAPK signaling pathways, thereby affecting of PI3K/AKT and MAPK signaling in ALL cells." (PMID 32054205, 2020).
Coffin-Siris syndrome (9 papers, 2021 to 2025). Coffin-Siris syndrome (CSS) is a rare congenital multi-systemic genetic disorder characterized by aplasia or hypoplasia of the distal phalanx or nail of the fifth digit, developmental delay, intellectual disability, coarse facial features, and other variable clinical manifestations. "In the present investigation, two novel SOX4 mutations were implicated with AF as a notable clinical feature of Coffin–Siris syndrome, thus expanding the SOX4-linked phenotypic spectrum." (PMID 39518344, 2024). "Recently, pathogenic SOX4 variants have been identified in several patients who had clinical features overlapping with Coffin–Siris syndrome." (PMID 36834931, 2023). "In addition, de novo variants of SOX4 have been described as causative for Coffin–Siris syndrome 10 (OMIM: #618506) and, very recently, even more pathogenic variants have been described in 17 patients." (PMID 36834931, 2023). "Intriguingly, mutations in SoxC proteins, Sox4 and Sox11, are associated with a developmental disorder called Coffin-siris syndrome (CSS), and one key characteristic of CSS patients is craniofacial defects." (PMID 39005444, 2024). "In particular, mutations in Sox4 and Sox11, most of them being point mutations in the HMG box, are associated with a developmental disorder called Coffin-siris syndrome (CSS)." (PMID 39005444, 2024). "Pathogenic variants in this complex have been associated with a number of conditions, including Coffin-Siris syndrome (CSS, MIM 135900, ORPHA:1465), Nicolaides-Baraitser syndrome (NCBRS, MIM 601358) and other CSS-like conditions (SOX4)." (PMID 34205270, 2021). "SOX4 and SOX11 are BAF-complex targets, which accounts for why SOX4- and SOX11-related syndromes are similar to Coffin–Siris syndrome." (PMID 38094004, 2023). "SOX4- and SOX11-related syndromes often share some common features with Coffin–Siris syndrome, which is characterized by abnormal head size (microcephaly or macrocephaly) with characteristic facial features, digits, and eye abnormalities." (PMID 38094004, 2023).
esophageal squamous cell carcinoma (9 papers, 2018 to 2025). Esophageal squamous cell carcinoma (ESCC) is a type of esophageal carcinoma (EC) that can affect any part of the esophagus, but is usually located in the upper or middle third. "It has been shown that lncRNA miR205HG drives the advancement of esophageal squamous cell carcinoma through the miR-214/SOX4 axis." (PMID 37251440, 2023). "Related studies have shown that propofol can inhibit the invasion and metastasis of esophageal squamous cell carcinoma cells by downregulating the expression of SOX4." (PMID 34956562, 2021). "Studies reveal its role in regulating proliferation and migration in esophageal adenocarcinoma (EAC) cells and promoting growth and metastasis in esophageal squamous cell carcinoma (ESCC) by sponging miR-214 to upregulate SOX-4 expression." (PMID 40034693, 2025). "In esophageal squamous cell carcinoma (ESCC), SOX4 cooperates with EZH2 and HDAC3 to enhance tumor cell progression and metastasis through epigenetic silencing of miR-31 by H3K27me." (PMID 38331879, 2024).
medulloblastoma (9 papers, 2008 to 2025). A malignant, invasive embryonal neoplasm arising from the cerebellum. "De Bont showed that SOX4 is over expressed by about 11 fold in medulloblastoma compared with ependymoma and normal cerebellum." (PMID 20419098, 2010). "Expression of Sox4 and Sox11 has been shown to increase in many different types of human cancers, including basal cell carcinomas (BCC) and medulloblastomas." (PMID 23658834, 2013).
nasopharyngeal carcinoma (9 papers, 2015 to 2025). A carcinoma arising from the nasopharyngeal epithelium. "Upregulation of SOX4 is also associated with tumour development in nasopharyngeal carcinoma." (PMID 37251541, 2023). "Thus, LT triggers ferroptosis in nasopharyngeal carcinoma cells via regulation of SOX4/GDF15 axis." (PMID 40552277, 2025).
Obesity (9 papers, 2011 to 2025). Accumulation of substantial excess body fat. "The reduced thermogenic capacity of Sox4-MKO mice increases their susceptibility to diet-induced obesity." (PMID 39402212, 2025). "We found that, in association with their relative obesity, the iWAT of SOX4 AKO mice expressed significantly higher levels of pro-inflammatory genes F4/80 and Mcp1 vs. SOX4F/F mice." (PMID 36451857, 2022). "Consistent with an increased susceptibility to obesity, F4/80, a macrophage marker, was found to be significantly upregulated in the gWAT of HFD-fed Sox4-MKO mice compared to their Sox4f/f counterparts." (PMID 39402212, 2025). "Conversely, overexpression of SOX4 in BAT enhances thermogenesis counteracting diet-induced obesity." (PMID 39402212, 2025). "Due to decreased heat production and energy consumption, Sox4 MKO mice were prone to develop obesity and related metabolic diseases." (PMID 39402212, 2025). "Adipose specific knockout of Sox4 mice develop obesity with severe hepatic steatosis, insulin resistance, and inflammation." (PMID 39351529, 2024). "SOX4 adipocyte-specific knockout mice were easy to develop obesity and insulin resistance under HFD." (PMID 36451857, 2022). "Overexpression of SOX4 (Pref1-Sox4) suppressed HFD-induced obesity and relieved glucose intolerance as well as insulin resistance." (PMID 36451857, 2022). "Among these obesity-associated genes, three genes (NUGGC, EFR3B, and SOX4) were found to be upregulated or downregulated according to the presence of obesity both in the literature and in the current study." (PMID 34381138, 2021). "Sox4 reportedly has a role in insulin secretion in the adult β-cell downstream of the KATP channel, and is identified as a risk factor for diabetes and obesity." (PMID 21362171, 2011). "Our findings elucidate the regulatory role and mechanism of SOX4 in controlling thermogenic gene programs, and suggest that targeting SOX4 may provide a potential strategy for enhancing energy expenditure to combat obesity." (PMID 39402212, 2025). "Additionally, SOX4 suppresses adipocyte hyperplasia in obesity by promoting the conversion of adipogenic–non adipogenic cells." (PMID 39498440, 2024). "We further investigated whether overexpression of SOX4 in BAT could counteract HFD-induced obesity." (PMID 39402212, 2025). "Thus, SOX4 protein may potentially become a drug target for the treatment of obesity and metabolic syndrome." (PMID 36451857, 2022). "Elevated expression of SOX4 in mice resulted in upregulation of thermogenic genes and increased heat production, thereby mitigating HFD-induced obesity." (PMID 39402212, 2025). "Overall, these results demonstrate that overexpressing SOX4 in BAT increases energy expenditure and attenuates HFD-induced obesity." (PMID 39402212, 2025). "Our findings show that AAV-mediated overexpression of SOX4 enhances thermogenic capacity of BATs, helping mice resist HFD-induced obesity." (PMID 39402212, 2025). "Since SOX4 is necessary for thermogenic gene expression and thermogenic function of beige adipocytes and regulates energy consumption in cold stimulation, we further examined the effect of SOX4 on a high-fat diet (HFD) induced obesity." (PMID 36451857, 2022). "We investigated whether the absence of SOX4 in BAT contributes to obesity development." (PMID 39402212, 2025).